SIRPA (signal regulatory protein alpha)
Diseases named in the same sentence as SIRPA in open-access papers (continued):
Sharing a sentence is not in itself a finding about the gene and the disease.
tumor (continued). "As an innate immune checkpoint, CD47 on tumour cells can interact with the signal regulatory protein SIRPα on the surface of macrophages and send a ‘don't eat me’ signal to assist tumour cells to escape immune surveillance." (PMID 37974395, 2023). "Magrolimab is a novel humanized immunoglobulin G4 anti-CD47 antibody that improves tumor cell phagocytosis by inhibiting the binding of CD47 to SIRPα." (PMID 37894427, 2023). "Currently the clinically most advanced agents targeting myeloid checkpoints block the interaction between CD47 on tumor cells and the signal regulatory protein alpha (SIRPα) expressed on myeloid cells." (PMID 37346044, 2023). "Our findings here show the promising value of blocking the CD47/SIRPα axis to replenish immune mobilization in the tumor microenvironment, which is of clinical benefit for improving the low treatment response rate of CRC." (PMID 36626230, 2023). "Except for the interaction of CD47 on tumor cells with SIRPα on neutrophils, the knowledge about immune checkpoint molecules on neutrophils is limited." (PMID 37346044, 2023). "The antibodies targeting CD47 and SIRPα, either alone or in combination with tumor cell-specific opsonizing antibodies and T-cell checkpoint inhibitors, have shown promise in several trials for various malignancies." (PMID 35874659, 2022). "The CD47 and signal regulatory protein alpha (SIRPα) which overexpressed on exosomes derived from tumor cells, helped the nanoparticles to escape from the clearance of the mononuclear phagocyte system (MPS)." (PMID 36003616, 2022). "D4–2, a macrocyclic peptide targeted to mouse SIRPα was designed to inhibit the interaction between CD47 and SIRPα and promote macrophage-mediated phagocytosis of tumor cells when combined with rituximab." (PMID 35418166, 2022). "SIRPα recognizes the elevated levels of CD47 on tumor cells and negatively controls effector function which prevents destruction of the cancer cells." (PMID 36369063, 2022). "An EV-based immune checkpoint blockade that antagonizes the interaction between CD47 and signal regulatory protein alpha (SIRPalpha) to block the “don’t eat me” signal CD47 at the tumor site has been described." (PMID 36498469, 2022). "Subsequently, we evaluated the antitumour ability of OH2 and anti-SIRPα combined therapy in a tumour-bearing mouse model." (PMID 36310169, 2022). "CD47 on tumor cells can bind to its ligand, signal regulatory protein α (SIRPα), on macrophages, thereby inhibiting macrophage phagocytosis." (PMID 36274066, 2022). "Inhibition of SIRPα-CD47 interaction by anti-CD47 or anti-SIRPα antibody leads to a significant increase in cancer cell phagocytosis by macrophages and a decrease in tumor burden." (PMID 36135216, 2022). "Among those immune checkpoint genes, both CD47 and SIRPA were remarkably upregulated in the hot tumor group." (PMID 35211415, 2022). "Most SIRPα mAbs induce antibody‐dependent cellular phagocytosis (ADCP) of cancer cells in combination with opsonizing antibodies that target tumour antigens." (PMID 35908284, 2022). "For example, the binding of CD47 to signal regulatory protein α (SIRPα) on macrophages reduces their anti-tumor response, which can be restored by blocking this interaction." (PMID 35865547, 2022). "Potent antitumor activity was observed in response to humanized anti-SIRPα antibody hAB21combined with rituximab or PD-1/PD-L1 blockade in tumor-bearing mice." (PMID 35837100, 2022). "Our anti-SIRPα blocked macrophages also proved to be effective in combination with tumor opsonization." (PMID 35454837, 2022). "Since the discovery of the first tumor phagocytosis-related checkpoint, namely the CD47/SIRPα axis, in the late 2000s, other tumor phagocytosis-related checkpoints have been identified: the PD-1/PD-L1 axis, MHC-I/LILRB1 axis, and CD24/SIGLEC-10 axis." (PMID 35978372, 2022).
tumor (continued). "By combining a TAA-targeting mAb and anti-CD47 or anti-SIRPα mAb, immune cells can be recruited to the tumor and become fully activated by one antibody." (PMID 35884427, 2022). "Its binding to signal-regulated protein α (SIRPα) signals cancer cells to escape from macrophage-mediated phagocytosis, thereby promoting tumor progression." (PMID 35433462, 2022). "The combination of OH2 and anti-SIRPα also showed stronger regulation of the tumour immune microenvironment." (PMID 36310169, 2022). "Quite a few anti-CD47 and anti-SIRPα antibodies are already undergoing clinical trials for tumor treatment." (PMID 35746616, 2022). "Our earlier studies also showed that sorting of macrophages/monocytes from marrow gave the same results in terms of tumor suppression as unsorted marrow, likely because those cell fractions are the main marrow cell types that express SIRPα." (PMID 35454837, 2022). "The binding of CD47 (cluster of differentiation 47) on tumor cells to SIRPα (signal-regulatory protein α) ligand on macrophages is a typical tumor escape mechanism." (PMID 36071472, 2022). "The anti-BAG3 + anti-SIRPα mAbs treatment inhibited (p = 0.007) tumor growth by about the 70%; also the number of metastatic lesions was decreased, mostly by the effect of the anti-BAG3 mAb." (PMID 35241649, 2022). "CD47 is a marker of self-recognition present on tumour and normal tissue that precipitates an anti-phagocytic signal upon binding to the signal regulatory protein alpha (SIRPα) transmembrane protein on the surface of macrophages." (PMID 35954487, 2022). "A novel recombinant SIRPα-Fc fusion protein, IMM01, was constructed and produced using an in-house developed CHO-K1 cell expression system, and the anti-tumor mechanism of IMM01 targeting the CD47-SIRPα pathway was explored." (PMID 36384978, 2022). "The CD47/SIRPα axis is the predominant mechanism by which tumor cells resist macrophage phagocytosis." (PMID 35965509, 2022). "Ultimately, the combination of SIRPα–ferritin and the doxorubicin prodrug eradicated colorectal cancer and elicited tumor-specific memory." (PMID 35566065, 2022). "In tumor-bearing mice, exosomes containing SIRPα antagonists were observed to significantly promote tumor phagocytosis." (PMID 35800056, 2022). "Sensitivity analysis shows that the most influential parameters are densities of PD-1 and SIRPα on TAMs, Hill function parameters for inhibition on phagocytosis; and rates of TAMs recruitment, polarization, and phagocytosis for tumor growth." (PMID 35856032, 2022). "CD47 is a well-documented “don’t eat me” signal which interacts with the signal regulatory protein alpha (SIRPα) on the surface of macrophages, therefore protecting tumor cells against macrophagic phagocytosis." (PMID 36080223, 2022). "In the present study, it is possible that donor T cells respond to recipient SIRPα as an alloantigen, and thus create a late-appearing set of T cells enacting both cGVHD and tumor regression." (PMID 35874659, 2022). "The attachment of signal regulatory protein alpha (SIRPα) on macrophages to CD47, a “don’t eat me” signal on cancer cells and colony-stimulating factors, secreted by cancer cells, polarize tumor-associated macrophages (TAMs) to a tumorigenic M2 phenotype." (PMID 36612158, 2022). "In the ex vivo analysis, we found that the treatment with either anti-BAG3 or anti-SIRPα mAb resulted in a reduction of tumor weight, which was more impressive when the two antibodies were used in combination." (PMID 35241649, 2022). "Generally speaking, in the tumor microenvironment, when interacting with signal regulatory protein-alpha (SIRPα) which is expressed on macrophages, CD47 can realize the function of “do not eat me”." (PMID 36660426, 2022). "Subsequently, SIRPα–ferritin antagonized against CD47 for further enhanced tumor-specific immunity, achieving synergistic antitumor effects." (PMID 35566065, 2022).
tumor (continued). "Interactions between CD47 on tumor cells and SIRPα on neutrophils inhibit neutrophil effector functions, allowing the tumor to escape immune surveillance." (PMID 35884427, 2022). "For example, CD47–signal regulatory protein α (SIRPα) axis has been proven critical for the tumor to escape from macrophage-mediated phagocytosis." (PMID 36497444, 2022). "Inhibition of glutaminyl cyclases in tumor cells by small molecules has been shown to inhibit binding of soluble SIRPα-Fc fusion proteins and to enhance myeloid cell activation against tumor cells." (PMID 36052078, 2022). "For instance, signal regulatory protein α (SIRPα) inhibits macrophage phagocytosis of tumor cells by interacting with CD47." (PMID 35800056, 2022). "CD47, a receptor overexpressed on tumor cells, recognized the signal-regulatory protein α (SIRPα) on macrophages and protected the tumor cells from phagocytosis." (PMID 36311702, 2022). "The propensity of tumor cell CD47 to bind to signal regulatory protein alpha (SIRPα) on the macrophage, thus creating a checkpoint, spares the tumor cell from phagocytosis." (PMID 36276103, 2022). "The anti-phagocytic inhibitory signal was removed or reduced through downregulation of both CD47 and SIRPα gene expression on tumor cells and macrophages, respectively." (PMID 35418166, 2022). "As a crucial phagocytosis signaling pathway between macrophages and tumors, CD47/SIRPα axis is likely to be an effective target for tumor immunotherapy." (PMID 35410993, 2022). "The elevated expression of CD47 in cancers prevents macrophage phagocytosis and the anti-human CD47 antibody B6H12 prevents tumor growth in several xenograft models by preventing SIRPα engagement." (PMID 36233088, 2022). "In immunocompetent C57BL/6 mice, xenografted MC38 colon cancer cells treated with PD‐L1 mAb and SIRPα‐Fc significantly reduced tumour growth compared to monotherapy." (PMID 35908284, 2022). "Systemic injection of macrophages coated by antibodies for tumor targeting and for SIRPα blocking can repress tumor growth." (PMID 35600645, 2022). "At the same time, SIRPα-expressing ferritin induced massive phagocytosis of tumor cells by macrophages by blocking the SIRPα/CD47 pathway." (PMID 35566065, 2022). "We demonstrate this strategy in two different models of metastasis by CD47 deletion and by adoptive transfer of SIRPα-blocked marrow cells in combination with tumor-opsonizing IgG." (PMID 35454837, 2022). "Targeting CD47/SIRPα represents a novel approach to enhance anti-tumor immunity by augmenting or reactivating critical tumor clearance mechanisms, as a key immune checkpoint in different cancers similar to that of the PD-1/PD-L1 checkpoint for solid tumors." (PMID 36080360, 2022). "SIRPα inhibitors targeting macrophages have emerged as a strategy to break down tumor inhibition of macrophages." (PMID 35892835, 2022). "CD47, an inhibitory ligand expressed on tumor cells, often interacts with SIRPα on macrophages to transmit a “don’t eat me” signal to escape the phagocytosis by macrophages." (PMID 35410993, 2022). "Studies in immunocompetent animal models suggest that adaptive immune responses subsequent to CD47/SIRPα blockade are significantly involved in tumor growth control." (PMID 35538512, 2022). "It is known that CD47 is overexpressed on the surface of most tumors and interacts with signal regulatory protein α (SIRPα) on phagocytes, which greatly limits the ability of macrophages to phagocytize tumor cells." (PMID 34973131, 2022). "It was reported that SIRP-1 antibodies induce macrophage internalization of SIRPα, reducing the availability of SIRPα to bind to tumor cells." (PMID 36429020, 2022). "Despite the significant association between the SIRPα/CD68-ratio in the invading front and inner tumor areas (p < 0.0001, r = 0.75), the ratio differed in 30/98 cases." (PMID 35406573, 2022).
tumor (continued). "In BALB/C mice, murine SIRPα‐Fc‐CD40L increased tumour rejection rates and long‐term immunity compared to treatment with CD47 mAb, CD40 agonist antibody, or the combination of these." (PMID 35908284, 2022). "Blockade of the CD47/SIRPα interaction can inhibit tumor growth by inhibiting the suppressive effects of SIRPα and promoting macrophage activity." (PMID 36080360, 2022). "Tumor cell killing by myeloid cells can be improved by disrupting CD47/SIRPα interactions, for example with CD47 blocking antibodies." (PMID 36052078, 2022). "ADCP and ADCC are negatively regulated by interactions between CD47 on tumor cells and signal regulatory protein alpha (SIRPα) on effector cells." (PMID 36052078, 2022). "We next assessed the functionality of STI-6643, by analyzing its ability to block the SIRPα/CD47 interaction in vitro using CD47-presenting tumor cells and recombinant human SIRPα protein." (PMID 35664753, 2022). "CD47 on tumor cells and SIRPα on TAMs facilitate a “don't-eat-me” signal which prevents cancer cells from immune clearance." (PMID 36970051, 2022). "A direct association was also noted with the SIRPα/CD68-ratio (p = 0.04, r = 0.21 for the invading front; p = 0.03, r = 0.21 for inner tumor areas)." (PMID 35406573, 2022). "CD47 is a well-known target in tumor immunology, which binds with the signal regulatory protein alpha (SIRPα, also known as CD172a) on macrophages, sending the signal of 'don't eat me'." (PMID 36185609, 2022). "Researchers designed exosomes containing SIRPα variants as immune checkpoint blockers, thereby antagonizing the interaction between CD47 and SIRPα, inducing enhanced tumor phagocytosis, and triggering an effective anti-tumor T-cell response." (PMID 35890175, 2022). "Therapeutic blockade of the CD47/SIRPα axis by small molecules or monoclonal antibodies (mAbs) is a proven strategy to enhance macrophages-mediated anti-tumor activity." (PMID 35664753, 2022). "Anti-cancer treatments (e.g., immunotherapy) by intervening the binding affinity of CD47 to SIRPα contribute to the adaptive immune response and tumour cells phagocytosis." (PMID 36203878, 2022). "CD47 or SIRPα blockade enables elimination of tumor cells, especially when combined with antitumor antibodies for macrophage-mediated cellular phagocytosis via the Fc domains of the bound antibody." (PMID 35565307, 2022). "SIRPα-exosomes inhibited tumor growth by binding to and suppressing the function of CD47, a “don’t eat me” signal overexpressed on cancer cells, therefore promoting the engulfment of tumor cells by macrophages." (PMID 35054611, 2022). "Our previous study has demonstrated that selective blockade of the CD47/SIRPα axis on Raji tumor cells with NI-1701 reduced tumor growth in vivo." (PMID 35538512, 2022). "Both M1 and M2 macrophages are receptive to the action of CD47 monoclonal antibodies or SIRPα fusion proteins to exert their anti-tumor effects." (PMID 36158683, 2022). "This study also provides novel insight on how this CD47- SIRPα should be manipulated for tumor immunotherapy." (PMID 35511221, 2022). "Now, tumor immunotherapy targeting the CD47/SIRPA axis has also become a hotspot in cancer treatment." (PMID 35211415, 2022). "Researchers demonstrated that combined SIRPα-Fc and CQ treatment interrupted the CD47/SIRPα axis and disrupted the protective autophagy in tumor cells, enhanced phagocytosis of macrophages, and then activated CD8+ T cell-mediated anti-tumor immune." (PMID 36300110, 2022). "As an alternative to anti-CD47 antibodies, anti-SIRPα antibodies have also been studied for their ability to promote tumor elimination." (PMID 35884427, 2022). "Tumor cells were programmed to overexpress SIRPα and PD-1 and then extracted for cellular vesicles to simultaneously block innate and adaptive immune checkpoints in vivo." (PMID 35874757, 2022).
tumor (continued). "In conclusion, our study indicates that the phagocytosis checkpoints of the PD1/PDL1 axis and CD47/SIRPα are enhanced in the tumor tissues of ICC patients and especially in HBV infection patients." (PMID 35317832, 2022). "Studies have shown that blocking the CD47/SIRPα signaling pathway between tumor cells and phagocytes can increase the phagocytosis of tumor cells by innate immune cells, thereby enhancing the antitumor immune response." (PMID 35566065, 2022). "More SIRPα+ or PD1+ TAMs were observed in the tumor tissues of ICC patients with HBV infections compared to non‐HBV‐infected patients." (PMID 35317832, 2022). "Expressed CD47 on tumor cells can bind to SIRPα on the macrophages and inhibit phagocytosis of tumor cells." (PMID 36018888, 2022). "In a second approach, we modify marrow macrophages for an adoptive cell therapy by pre-blocking SIRPα and pre-loading Fc-receptors with tumor-opsonizing IgG prior to infusion." (PMID 35454837, 2022). "Agents targeting CD47 or its ligand SIRPα have exhibited efficacy in tumor-bearing mouse models and human trials." (PMID 35837100, 2022). "In fact, SIRPα‐blocked macrophages primed with tumor targeting antibody have been reported to traffic to solid tumor after intravenous injection." (PMID 35600645, 2022). "Binding to CD47, the SIRPα-Fc fusion protein can block the immunosuppressive CD47–SIRPα signal between macrophages and tumor cells as a decoy receptor and has demonstrated its immunotherapeutic efficacy in various tumors." (PMID 36080360, 2022). "For example, the humanized anti-CD47 monoclonal antibody CC-90002 enables tumor cells killed by macrophages by blocking the CD47/SIRPα interaction." (PMID 35433462, 2022). "Targeting the CD47/SIRPα axis has become a promising strategy to promote tumor elimination through innate immunity." (PMID 35418166, 2022). "Cancer cells exploit this negative regulatory mechanism by overexpressing CD47 on their surface to escape immune surveillance and blockade of SIRPα/CD47 interaction is reported to enhance anti-tumor ADCP and ADCC." (PMID 36077152, 2022). "Given the crucial role of the CD47-SIRPα axis in tumor progression, we next evaluated the expression level of SIRPα in macrophages cultured with 4MU CM." (PMID 35410993, 2022). "Preclinical data demonstrated that selective SIRPα blockade stimulated T-cell recruitment into the tumors by restoring macrophage chemokine secretion, promoting tumor-antigen cross-presentation." (PMID 36429020, 2022). "Since tumor-cell phagocytosis by monocytes/macrophages has been extensively described as a key mechanism of action of CD47/SIRPα blocking molecules, we have explored the phagocytic activity of these cell populations in the TME." (PMID 35538512, 2022). "Although monotherapy with anti-CD47 or SIRPα has failed in clinical studies, anti-CD47 or SIRPα in combination with conventional therapies has shown significantly increased anti-tumor activities, especially in hematological malignancies." (PMID 35317832, 2022). "The binding of CD47 to its cognate receptor signal-regulatory protein alpha (SIRPα) on phagocytic cells leads to inhibition in the macrophage-mediated tumor cell phagocytosis." (PMID 35428347, 2022). "Anti-SIRPα monotherapy was effective in inhibiting tumor growth and preventing metastasis in highly enriched myeloid cells, triple-negative breast cancer, and mesothelioma." (PMID 36429020, 2022). "Therapeutic targeting of CD47, a surface glycoprotein and “don’t eat me” signal expressed on immune and tumor cells, which interacts with SIRPα on macrophages to suppress phagocytosis, is also being investigated." (PMID 33572196, 2021). "One such approach involves blocking the binding between CD47 and signal regulatory protein alpha (SIRPα), increasing tumor cell phagocytosis by macrophages." (PMID 33801234, 2021).